LINC01107 (long independently transcribed non-coding RNA 1107)
Gene: Long non-coding RNA gene on chromosome 2 (238,498,678 to 238,555,054, reverse strand). Ensembl gene ENSG00000225493.
Diseases named in the same sentence as LINC01107 in open-access papers:
LINC01107 is named in the same sentence as 2 diseases in open-access papers, as found by Europe PMC text mining. Sharing a sentence is not in itself a finding about the gene and the disease. The quoted sentences say what the papers report.
neurological disease (1 paper, 2022). "However, the gene set in our final selection (AARS, FBXW7, and LINC01107) was associated with brain functions, psychiatric disease and neurological disease." (PMID 36712885, 2022).
LINC01107 also shares sentences with these, for which no sentence is quoted: psychiatric disease (1 paper).